CCL2 (C-C motif chemokine ligand 2)
Diseases named in the same sentence as CCL2 in open-access papers (continued):
Sharing a sentence is not in itself a finding about the gene and the disease.
acute respiratory distress syndrome (54 papers, 2008 to 2025). Progressive and life-threatening pulmonary distress in the absence of an underlying pulmonary condition, usually following major trauma or surgery. "In COVID-19-associated cytokine storms, heightened expression of CXCL10, CXCL8, and CCL2 has been implicated in the pathogenesis of acute respiratory distress syndrome (ARDS)." (PMID 41268545, 2025). "Increased production of the CCL2 chemokine has previously been shown to be associated with severe acute respiratory distress syndrome (ARDS) caused by coronavirus 2 (SARS-Cov)." (PMID 35327350, 2022). "In severe cases the disease progresses into an Acute Respiratory Distress Syndrome (ARDS), which in turn depends on an overproduction of cytokines (IL-6, TNFα, IL-12, IL-8, CCL-2 and IL1) that causes alveolar and vascular lung damage." (PMID 32922210, 2020). "As an example, BALF-EVs increase interleukins IL-1β and IL-6, Tumor Necrosis Factor α (TNFα), and CC motif chemokine Ligand 2 (CCL2) in sarcoidosis disease and acute respiratory distress syndrome (ARDS)." (PMID 36768664, 2023). "In acute respiratory distress syndrome, CCL2 and CXCL10 affect the recruitment of neutrophils." (PMID 37958973, 2023). "A recent study reported that in acute respiratory distress syndrome (ARDS), CCL2, and CCL7 synergize with CXCL8 to promote neutrophil migration." (PMID 29018439, 2017). "Also, CCL2 and CCL7 chemokines are known to work synergistically with CXCL8 to drive neutrophil trafficking to the lungs during acute respiratory distress syndrome (ARDS)." (PMID 34737734, 2021). "The resulting acute respiratory distress syndrome (ARDS) and extrapulmonary multi-organ dysfunction are provoked by the excessive production of pro-inflammatory cytokines (IL-6, CXCL8) and chemokines (CXCL10, CCL5, CCL2), a phenomenon also referred as cytokine storm." (PMID 35013790, 2022). "In this vein, during acute respiratory distress syndrome (ARDS), recruited alveolar neutrophils and Mos/macrophages acquire a classically activated phenotype (Mo1/M1) responsible for the release of several growth factors and proinflammatory cytokines, including CXCL1, CXCL2, CXCL10, CCL2, and TNF-α." (PMID 39940787, 2025).
endotoxemia (54 papers, 2008 to 2025). "The proposed protective role of CCL2 in acute injury settings recapitulates earlier findings indicating that CCL2 neutralization caused enhanced mortality in a murine model of lethal endotoxemia." (PMID 23091461, 2012). "There exist differences in the cellular distribution of the CCL2 peptide in frontal cortex GM and subcortical WM–CC, in both the physiological condition and experimental endotoxemia." (PMID 35354428, 2022). "For example, CCL2 was previously shown to protect mice from endotoxemia." (PMID 28993690, 2017). "In a study using male and female rats, ethanol-fed female rats were found to have more severe liver injury as well as increased endotoxemia, lipid peroxidation, NF-kappa B activation, and upregulation of chemokines MCP-1 (CCL2) and MIP-2 (CXCL2)." (PMID 38370409, 2024). "This study addressed the role of monocyte chemoattractant protein-1 (MCP-1, also known as CCL2), in the pathogenesis of diaphragmatic inflammation and weakness during endotoxemia." (PMID 20950459, 2010).
acute kidney injury (49 papers, 2012 to 2025). Sudden and sustained deterioration of the kidney function characterized by decreased glomerular filtration rate, increased serum creatinine or oliguria. "In acute kidney injury, Brahma‐related gene 1 can continuously increase the binding of RNA polymerase II to the CCL2 gene by mediating chromatin remodelling, thus promoting hypoxic‐stress‐induced kidney proximal tubule CCL2 expression." (PMID 36872292, 2023). "Based on the importance of CCL2 in acute kidney injury, we selected CCL2 as the monocyte chemokine to be detected." (PMID 36793712, 2023). "The Ccl2 gene encodes monocyte chemoattractant protein 1 (MCP-1), which is an emerging biomarker in acute kidney injury and a crucial chemoattractant regulator of macrophages in the renal inflammatory response." (PMID 35990655, 2022). "In a mouse model of rhabdomyolysis-induced acute kidney injury, CD11bhighF4/80low macrophages expressed more transcripts of genes involved in disease progression, including Ccl2, fibronectin and collagen." (PMID 30456449, 2019). "CCL2 is one of the main chemoattractants of monocytes and has previously been described as a potential biomarker of severe tissue complications and systemic complications such as acute renal failure." (PMID 36977086, 2023). "In addition, CXCL-8 was shown to be produced exclusively by this group, together with the CCL-2 molecule, which highlights these molecules as potential indicators of acute kidney injury resulting from Bothrops envenomation." (PMID 36117588, 2022). "MCP-1 or Ccl2 (Chemokine -CC motif Ligand 2) recruits monocytes, T-cells and dendritic cells at site of renal injury/inflammation and plays a significant role in the progression of renal failure." (PMID 29091707, 2017). "Moreover, we noted that subsets of non-dilated proximal tubules in young postnatal mutants ectopically expressed Shh, Ccl2, and Kim1, all known to be activated by acute kidney injury." (PMID 27853247, 2016). "As ectopic tubular Shh and Ccl2 expression is seen after acute kidney injury (AKI), we interrogated another bone fide AKI marker, Kim1 and noted ectopic expression in P7 non-dilated proximal tubules." (PMID 27853247, 2016).
retinal degeneration (48 papers, 2010 to 2025). Degeneration of the retina. "Concurrently, elevated plasma concentrations of IL-6 and MCP-1/CCL2 reflect a chronic inflammatory state associated with retinal degeneration." (PMID 41301489, 2025). "A number of these transcripts have well-established links to retinal degeneration, including chemokine C-C motif ligand 2 (Ccl2) and rho-associated protein kinase 2 (Rock2)." (PMID 34465369, 2021). "Previous studies have shown that CCL2/CX3CR1 deficient mice on C57BL/6N background (with rd8 mutation) have an early onset (6 weeks) of spontaneous retinal degeneration." (PMID 23637822, 2013). "Our data demonstrates that the genetic inactivation of either Ccl2 and/or Cx3cr1 chemokine signalling differentially modulates the severity of the retinal degeneration caused by the Crb1RD8/RD8 mutation at 8 weeks of age." (PMID 22545116, 2012). "In the eye, ccl2 has been shown to play a role in the development of retinal degeneration; ccl2-deficient mice develop age related macular degeneration (AMD) like symptoms." (PMID 20844572, 2010). "Mice deficient in CCL2 or its receptor develop retinal degeneration with many pathological similarities to AMD." (PMID 20029141, 2010). "The evidence suggesting that CCL2 deficiency produces retinal lesions that resemble AMD has been called into question because of the presence of the rd8 mutation in C57BL/6N strain as this mutation can also produce retinal degeneration." (PMID 34869411, 2021). "The activation of canonical Wnt signaling might contribute to the focal retinal degeneration of mouse models with Ccl2 and Cx3cr1 deficiency, and intravitreal anti-LRP6 antibody therapy might be beneficial via deactivation of the canonical Wnt pathway." (PMID 26476672, 2015). "Stimulated by IL-1β, MG produces more chemokines (Ccl2, Cxcl1, and Cxcl10), which are involved in retinal degeneration." (PMID 35573676, 2022). "This 5-day PD acute retina degeneration model, combined with our discoveries in the chronic PKD environment, indicates that the replacement of miR-124 modulates the retinal degeneration at least partially with CCL2." (PMID 34681723, 2021). "The authors found that IL-33 was released by Müller cells after light exposure, which then induced CCL2, IL-6 and IL-1β expression through autocrine activation of Müller cells and promoted immune cell infiltration and retinal degeneration." (PMID 31796062, 2019). "Together, these data show that Müller glia transiently express CCL2 during the initial phase of the retinal degeneration and further reveal them to be the predominant source of retinal CCL2." (PMID 30553275, 2018). "Particularly strong CCL2 staining was evident in individual cells that resembled Müller glia cells (red), consistent with other models of retinal degeneration." (PMID 30553275, 2018). "Compared to normal mice, retinal degeneration in CX3CR1−/− mice was paralleled by increased CCL2 induction and retinal CCR2+ monocytes infiltration." (PMID 28320442, 2017). "Chemokine expression is prominent in many retinal degenerations, including AMD, wherein the up-regulation of genes encoding potent ligands such as Ccl2 and Cxcl10 is a characteristic of the disease." (PMID 28438165, 2017). "Several cytokines and chemokines including MIP-1α (CCL3), MIP-1β (CCL4), MCP-1 (CCL2), MCP-3 (CCL7), TNF-α, IL-1β and IL-6 have been implicated in photoreceptor-microglial crosstalk and retinal degeneration." (PMID 27814376, 2016). "The findings of the current study confirm a key role for Müller cells and Ccl2 in the retinal neuroinflammatory response in the light-damage model of retinal degeneration." (PMID 22992301, 2012). "Ccl2/Cx3cr1 double knockout (CCDKO) mice show an early onset retinal degeneration and have been suggested as a model for AMD." (PMID 22545116, 2012). "Nevertheless, the models allowed us to investigate the casual roles of monocyte malfunction (as a result of CCL2 or CCR2 depletion) in age-related retinal degeneration." (PMID 21850237, 2011).
retinal degeneration (continued). "The suppression of Ccl2 in MG, mediated by siRNA, attenuates detrimental inflammatory responses by reducing microglial recruitment and reduces photoreceptor death following rat retinal degeneration." (PMID 35573676, 2022). "Furthermore, CCL-2 is generated by Müller cells and involves the infiltration of microglia/monocytes and photoreceptor death in light-induced retinal degeneration." (PMID 30979028, 2019). "It was shown that IL-33 production by Müller cells was able to induce the expression of other chemokines and cytokines, including CCL2, which has been shown to be produced primarily by Müller cells in retinal degenerations to recruit macrophages into the site of damage." (PMID 31379825, 2019). "Moreover, the adoptive transfer of anti-retinal AAbs obtained from RCS rats with inherited retinal degeneration induced disruption of the blood–retinal barrier, upregulation of MCP-1 (CCL2) chemokine, and attracted macrophages/microglia into the retina." (PMID 29713325, 2018). "Additionally, we have shown that expression of Ccl2 is upregulated in Müller cells in light-induced retinal degeneration, and targeted knockdown of Ccl2 with siRNA reduces recruitment of microglia/monocytes and photoreceptor death." (PMID 25595590, 2015). "We have recently shown that in the light-induced model of retinal degeneration, suppression of Ccl2 expression with a targeted small-interfering RNA (siRNA) inhibits recruitment of IBA1-positive monocytes/microglia, and reduces photoreceptor death in the retina." (PMID 24705166, 2014). "In this study we therefore compare the newly established (rd8 mutation-free) chemokine knockout mouse lines to investigate whether individual or combined defects in Ccl2 and/or Cx3cr1 signalling result in retinal degeneration with age." (PMID 23232206, 2013). "The contribution of CCL2 depletion to age- and light-mediated retinal degeneration may be related to altered monocyte and macrophage function in these mice." (PMID 23637822, 2013). "We now provide evidence that the early onset retinal degeneration, observed in these CCDKO knockout mouse lines as well as in all re-derived “affected” Ccl2 and Cx3cr1 and Ccl2/Cx3cr1 double knockout mice, is caused by a third independent autosomal recessive locus." (PMID 22545116, 2012). "Conversely, it has been previously suggested that aging Ccl2−/− Ccr2−/− mice develop AMD-like retinal degeneration, indicating that a degree of Ccl2 signaling is also required for homeostasis, although the AMD-like phenotype in the knockout has been questioned." (PMID 22992301, 2012). "Therefore this data suggests that Ccl2 does not have a significant effect on the manifestation of the early onset retinal degeneration in mice that carry a homozygous RD8 mutation, although we cannot exclude a mildly protective effect of Ccl2 deficiency." (PMID 22545116, 2012). "This indicates that neither Ccl2 nor Cx3cr1 deficiency alone nor the combined double knockout of both chemokines leads to a pronounced early onset retinal degeneration." (PMID 22545116, 2012). "In order to understand phenotypic discrepancies in different chemokine knockout lines and to study how defects in Ccl2 and/or Cx3cr1 signalling contribute to the described early onset retinal degeneration, we defined primary and secondary pathological events in CCDKO mice." (PMID 22545116, 2012). "We have shown previously that the expression of Ccl2 is upregulated in Müller cells in a light-induced model of retinal degeneration, which coincides spatiotemporally with the local recruitment of microglia/monocytes and the region of peak photoreceptor death." (PMID 22992301, 2012). "Ccl2 is particularly well-characterized in the retina, and knockout studies indicate that ablation of Ccl2 or its receptor Ccr2 reduces monocyte infiltration and retinal degeneration in experimental choroidal neovascularization (CNV) and in light-damaged Cx3cr1−/− mice." (PMID 25595590, 2015).
retinal degeneration (continued). "Furthermore, mice deficient in CX3CR1 age-dependently develop AMD-like lesions, and mice deficient in both CCL2 and CX3CR1 have an early onset of retinal degeneration, although recent studies suggest that pathologies in the CCL2/CX3CR1 double knockout (DKO) mice is related to the Crb1 rd8 mutation." (PMID 23637822, 2013). "Furthermore, the persistent gliosis and gliotic scar formation in Cdc42-KD mice may also be detrimental and contribute to retinal degeneration through the secretion of pro-inflammatory cytokines such as TNFα and CCL2." (PMID 23372671, 2013). "Using the CCL2/CX3CR1 double knockout mouse model (DKO), which demonstrates RPE damage and retinal degeneration, we uncovered an interaction between PEDF and the TEP which is likely to play an important role in retinal ageing and in the pathogenesis of AMD." (PMID 30160348, 2018). "Several of these chemokines, including CCL2, CXCL1 and CXCL10 are involved in leukocyte recruitment in CNS diseases and in retinal degeneration." (PMID 28438165, 2017). "CCR2 deletion blocked retinal degeneration, suggesting that CX3CR1 usually represses CCL2 over-induction and recruitment of neurotoxic levels of CCR2+ monocytes." (PMID 28320442, 2017). "Ccr2 is a therapeutic target for retinal degenerative disorders including AMD and RP because deletion of Ccl2, a cognate ligand for Ccr2, can rescue PCD in Mertk−/− mice and deletion of Ccr2 ameliorated retinal degeneration in another model." (PMID 26458944, 2015). "We studied the effects of PEDF on focal retinal lesions in DKO rd8 (Ccl2−/−/Cx3cr1−/− on C57BL/6N [Crb1rd8]) mice, a model for progressive, focal rd (retinal degeneration)." (PMID 24160756, 2013). "Certain chemokines, such as CCL2 and CX3CL1, appear to be crucial in subretinal microglia and macrophage accumulation observed in AMD, and participate in the development of retinal degeneration as well as in choroidal neovascularization." (PMID 21126357, 2010). "Our data reveals that the combined genetic deficiencies of CCL2 and CX3CR1 as well as the individual deficiencies are not sufficient to induce age-related retinal degeneration up to 14 months." (PMID 23232206, 2013). "This suggests that during normal ageing individual or combined genetic defects in CCL2 or CX3CR1 signalling alone are not sufficient to drive photoreceptor loss and age-related retinal degeneration above basal levels." (PMID 23232206, 2013). "The group also reported no retinal degeneration in 12–14 months old CCL2 KO, CX3CR1 KO and CCL2/CX3CR1 DKO mice housed under dim conditions (33 lux light intensity)." (PMID 23637822, 2013). "These mice show recruited macrophages and microglia and it is hypothesized that these macrophages in the absence of CCL2 cannot phagocytize C5a, leading to retinal degeneration." (PMID 34869411, 2021). "Mice lacking CCL2 (MCP-1) expression exhibit retinal degeneration similar to AMD." (PMID 34202702, 2021). "The CCL2/CCR2 axis is crucial in subretinal macrophage and microglia accumulation in retinal degeneration models and human AMD, and these findings implicate that CCL2/CCR2 inhibition may be a novel tool to limit inflammation and neurodegeneration in the retina." (PMID 26527153, 2015). "Inversely, this shows that neither the single nor the double knockout of the chemokines Ccl2 and/or Cx3cr1 does lead to an early onset inferior retinal degeneration since all unaffected lines show a similar very low number of any autofluorescent lesions in the fundus as wildtype mice." (PMID 22545116, 2012). "Ccl2 deficiency also does not significantly add to the exacerbated retinal degeneration seen in Cx3cr1−/−/Crb1RD8/RD8 mice suggesting that the effects of Ccl2 and Cx3cr1 signalling defects do not act synergistically on the manifestation of the retinal degeneration in Crb1RD8/RD8 mice." (PMID 22545116, 2012).
retinal degeneration (continued). "It is tempting to speculate that increased local levels of CCL2 observed during ageing and in AMD patients promote retinal degeneration, not directly, but by priming the retina for the infiltration of systemic pro-inflammatory monocytes." (PMID 23232206, 2013).
inflammatory bowel disease (47 papers, 2005 to 2025). A spectrum of small and large bowel inflammatory diseases of unknown etiology. "Further, this data supports the independent finding that MCP-1 (CCL2) levels are increased in patients with inflammatory bowel disease and correlate with disease severity." (PMID 25852821, 2015). "Perturbations of these processes, like the release of CCL2, inhibit the differentiation of macrophages to IMACs thus leading to (chronic) inflammatory bowel diseases (IBDs)." (PMID 23181472, 2012). "Other studies demonstrated a reduction in CCL2 using L. paracasei-derived postbiotics in an in vitro inflammatory bowel disease model or found that cell-free supernatants from different species (e.g., L. acidophilus) downregulated IL-8 expression in HT-29 cells." (PMID 40238399, 2025). "In inflammatory bowel disease (IBD), monocyte chemoattractant protein‐1 (MCP‐1/CCL2) orchestrated the migration of peripheral monocytes towards the inflamed intestinal mucosa by interacting with the CCR2 receptor expressed on monocytes." (PMID 39993960, 2025). "Another approach involves targeting upstream regulators of CCL2: F-box and WD repeat domain-containing protein 7 (FBXW7), an E3 ubiquitin ligase in the gut, promotes Ccl2 and Ccl7 expression, exacerbating inflammatory bowel diseases (IBDs)." (PMID 40867747, 2025). "During inflammatory bowel disease (IBD), inflammatory fibroblast subsets upregulate secretion of chemokines like IL-6, CXCL1, and CCL2, promoting neutrophil and macrophage infiltration." (PMID 41465375, 2025). "Furthermore, anti-TNF non-responders with inflammatory bowel disease had upregulated CCR2 expression, which might cause lower serum CCL2 levels than those seen in the responders." (PMID 34367126, 2021).